EGFR (epidermal growth factor receptor)
Diseases named in the same sentence as EGFR in open-access papers (continued):
Sharing a sentence is not in itself a finding about the gene and the disease.
tumor (continued). "Similarly, secondary bile acids like DCA can activate EGFR and its downstream pathways, accelerating cancer development, while others like UDCA show potential in inhibiting tumor growth through suppression of the PI3K/AKT and EGFR pathways." (PMID 39948481, 2025). "These analyses revealed reduced expression of PTEN and EGFR in tumor regions compared to non-tumor regions." (PMID 40710199, 2025). "In vivo, EGFR-targeted platforms led to higher tumor accumulation and efficient tumor suppression, unlike the non-targeted counterparts." (PMID 39940134, 2025). "SPs extracted from G. lemaneiformis and G. fisheri have demonstrated potent anti-tumour activities by inducing apoptosis through various mechanisms, including the upregulation of CD8+ T cells and IL-2, inhibition of EGFR/MAPK/ERK signalling pathways, and activation of the Fas/FasL pathway." (PMID 40077614, 2025). "Currently, the FDA has approved targeted therapies based on monoclonal antibodies (mAbs)—such as bevacizumab and cetuximab, which inhibit pathways crucial for tumor growth—angiogenesis through vascular endothelial growth factor (VEGF) inhibition, and the epidermal growth factor receptor (EGFR)." (PMID 40361403, 2025). "In another large cohort, 100 of 1173 (8.53%) NSCLC patients’ tumor were identified as RDAA positive that does not have known and targetable EGFR/ALK/ROS1 mutation or rearrangement." (PMID 40246819, 2025). "Moreover, positive correlations between its expression and EGFR-TKI resistance, CD8+ T cell infiltration and tumor proportion score (TPS) in LUAD were validated in patients’ samples, emphasizing its potential in guiding personalized therapy." (PMID 40529377, 2025). "Notably, the genomic amplification of receptor tyrosine kinases (e.g., EGFR, ERBB2) enhances the sensitivity of tumor cells to growth factors, sustaining their proliferative capacity." (PMID 41281744, 2025). "Moreover, miR-133a-3p can target multiple receptors, such as EGFR, FGFR1, IGF1R, and MET receptors, to inhibit tumor cells." (PMID 40170845, 2025). "This possibility is supported by the heterogeneity in PTEN and EGFR expression observed between tumor and non-tumor tissues in this case." (PMID 40710199, 2025). "Consistently, co-culture assays showed that B10-B11 enhances T cell cytotoxicity against dual-positive tumor cells by disrupting PD-L1 signaling, whereas monovalent B11 or controls lacking co-expression of EGFR failed to produce this effect." (PMID 41155373, 2025). "EGFR-mutant NSCLC poses a notable challenge in immuno-oncology; despite occasional PD-L1 expression, these tumors typically exhibit low TMB, limited CD8+ T cell infiltration, and an overall immunologically “cold” tumor microenvironment." (PMID 41584608, 2025). "Herein, in this review, introducing the frequently mutated gene EGFR in tumors and its abnormal activation are mainly focused on, highlighting that epidermal growth factor receptor (EGFR) wild‐type and mutants respond differently to ICBs via tumor‐intrinsic and tumor‐extrinsic manners." (PMID 40859900, 2025). "The impact of USP11 on EGFR signaling was validated using USP11-KO cells, which demonstrated reduced EGFR stability and in vivo tumorigenic effect, and diminished responses to EGF stimulation in migration, proliferation, and 3D tumor spheroid assays." (PMID 41419456, 2025). "Additionally, PM2.5 has been reported to activate the aryl hydrocarbon receptor (AhR), which promotes EGFR signalling and upregulates oncogenic factors such as TMPRSS2 and IL18, contributing to tumour progression." (PMID 40559957, 2025). "In addition, their inhibitory effects on EGFR and VEGFR-2, key targets for tumor growth and angiogenesis, were assessed." (PMID 40745188, 2025). "The top five genes with the highest degree values are AKT1, SRC, EGFR, BCL2, and CASP3, suggesting that FOA may exert its anti-tumor effects by acting on multiple targets." (PMID 41050420, 2025).
tumor (continued). "EGFR overexpression also strengthened the binding of PCBP2 with miRNAs containing this “GGGU” motif, thereby promoting their secretion through sEVs to support tumor angiogenesis." (PMID 39816681, 2025). "We found that CSCs expressed high levels of tumor stemness genes (PROM1, CD24, CD47, ANPEP, ALDH1A1, OLFM4, and SOX9), and demonstrated a high cancer stemness score, along with activation of the cancer driver genes EGFR and ERBB2." (PMID 39950944, 2025). "In addition, G31P-mediated CXCR1/2 inhibition disrupts the pathological feedback loop in the tumor microenvironment, where ELR+ CXC chemokines (CXCL1/8) activate CXCL8, leading to EGFR transactivation and sustained inflammatory signaling." (PMID 41425704, 2025). "Here we report that RAC1B, but not the conventional RAC1 isoform RAC1A, promotes tumor development, stabilizes EGFR, and can serve as an ideal therapeutic target in EGFR‐mutant LUAD." (PMID 40548642, 2025). "However, a growing body of evidence indicates that the interplay between the EGFR and VEGF/VEGFR pathways extends beyond this, involving a direct autocrine signaling loop within the tumor cells themselves." (PMID 41158851, 2025). "When specimens with similar tumor content were tested, cases with EGFR amplification had lower IC Ct values than those without EGFR amplification." (PMID 38687753, 2024). "Furthermore, ligand-receptor pairs related to EGFR between CXCR1+ neutrophils and tumor cells were significantly increased in resistance and communication with Treg cells also increased." (PMID 39638994, 2024). "Notably, TRIB3 is key stress regulators in a variety of tumors because its C-terminal domain can interact with ubiquitin ligases and various other proteins to promote tumor progression, such as AKT1, β-catenin, SQSTM1, TRIM8, EGFR, and TCF4." (PMID 39881875, 2024). "While T-BsAb targeting EGFR and mesothelin failed to significantly reduce tumor growth, HER2-targeted T-BsAbs displayed potent anti-tumor activity, eliminating tumors derived from two different cell lines with durable responses." (PMID 39139449, 2024). "We explored possible explanations for this effect of saracatinib in EGFR WT tumors and noted that there was no consistent increase in tumor size at animal sacrifice from those in other treatment groups." (PMID 38892466, 2024). "In the absence of EGFR, these tumours also failed to develop large vessel patterns and instead contained dense capillary networks, reminiscent of those observed in PN-GSC-initiated lesions." (PMID 38570528, 2024). "Thus, FASN inhibition provides an avenue by which pro-tumor effects of both MET and EGFR can be targeted." (PMID 39062731, 2024). "Moreover, differences in the expression profile of genes such as EGFR, PTEN, and PDGFR were observed within the same tumor nodi, which apparently indicate several cell lineages coexisting in the same tumors." (PMID 38672069, 2024). "Our study is the first to demonstrate a strong association between CD151 expression and the status of EGFR mutation, specifically noting a higher prevalence of CD151 expression in tumours lacking these mutations." (PMID 38982031, 2024). "To establish whether ecDNAs experience higher RS than the rest of the genome, we quantified the percentage of total nuclear pRPA2-S33 signal colocalized with EGFR in GBM39ec and GBM39HSR tumour cells." (PMID 39506153, 2024). "In murine tumor models with high EGFR expression, Erb-sumIL2 significantly enhanced tumor control when compared with the non-EGFR targeting sumIL-2, while also inducing protective memory immunity." (PMID 39664443, 2024).
tumor (continued). "Moreover, it effectively reduced tumor growth both independently and in combination with ICI or EGFR-targeted therapies in murine xenograft models, further supporting its clinical prospects." (PMID 39164274, 2024). "EGFR gene mutations and ALK gene fusion are both important driver genes in NSCLC, typically not co-occurring in the same tumor." (PMID 39582541, 2024). "Intriguingly, AZD9592 in vitro efficacy was most robust when both EGFR and c-MET were engaged, suggesting that bispecific targeting of EGFR and c-MET may increase tumor selectivity and reduce on-target toxicities." (PMID 39065587, 2024). "Given the high histidine content in rAj-HRP, it is plausible that it may similarly induce EGFR internalization in HCT116 cells, leading to tumor cell death." (PMID 39519855, 2024). "Alternatively, in non-inflammatory conditions, mutations in genes such as epidermal growth factor receptor (EGFR) can modulate signaling pathways, leading tumor cells to produce chemokines like CCL22 that enhance Tregs infiltration." (PMID 39744628, 2024). "We found that SRC inhibition alone or combined with anti-BRAF treatment with or without anti-EGFR did not affect the tumor growth in our resistant models (data not shown)." (PMID 39436710, 2024). "Additionally, targeting of MET similarly to other RTKs, such as EGFR, IGF1R, and VEGFR, increases tumor cytotoxicity to DDAs." (PMID 38957115, 2024). "While we did not look at MAPK in our analysis, we observed that there was an increase in proliferative markers EGFR and PCNA by PCR and EGF in serum in patients who received sorafenib/RT, which may enhance the proliferation of tumor cells." (PMID 38542325, 2024). "Importantly, ADAMTSL5 confers tumorigenicity by upregulating oncogenic inputs (i.e., MET, EGFR, PDGFRβ, IGF1Rβ, FGFR4), and its abrogation increases sensitivity of tumor cells to clinically relevant drugs." (PMID 38495872, 2024). "EGFR and HER2 T-BsAbs were constructed using the 2 + 2 IgG-[L]-scFv T-BsAbs format bearing two anti-CD3 scFvs attached to the light chains of an IgG to engage T cells while retaining bivalent binding to tumor antigens with both Fab arms." (PMID 38650005, 2024). "Nevertheless, to increase the potency of EGFR-targeting therapies such as CAR T cells and BiTEs without further enhancing on-target/off-tumor toxicity, strategies to improve the specificity for EGFR in the tumor tissue are urgently needed." (PMID 38492569, 2024). "Tecentriq is currently used in combination with Avastin (bevacizumab), paclitaxel and carboplatin (chemotherapy), for the initial (first-line) treatment of individuals with metastatic NSCLC with no EGFR or ALK genomic tumor aberrations." (PMID 38384472, 2024). "Previous studies have also demonstrated that prophylactic vaccination with human EGFR peptides can effectively break self-tolerance without inducing systemic autoimmunity, thus impeding tumor development." (PMID 39766327, 2024). "Neither IFN-γ nor aT-sEVs affected the secretion of EGFR+ sEVs in tumour cells, indicating that PD-1/CD80+ sEVs possibly participated in the specific mediation of immune-related sEV secretion in tumours." (PMID 38719909, 2024). "On the other hand, the expression of genes TOP1, EGFR, STAT3, NR3C1, VEGFA, and AR was upregulated, which could promote tumor cell growth." (PMID 38297292, 2024). "Previous reports have revealed that the tumor microenvironment of liver metastasis has an increased expression of the vascular endothelial growth factor, and in EGFR-mutant NSCLC, activated EGFR signaling drives vascular endothelial growth factor expression in a hypoxia-independent manner." (PMID 38361742, 2024). "Anti-EGFR AY13 mAb stained cells in normal and tumor tissue samples." (PMID 38883274, 2024). "Concurring with other data, low-level EGFR copy number gains are insufficient to qualify a tumor as EGFR-amplified and did not impact PFS or OS in our cohort." (PMID 38326661, 2024).
tumor (continued). "Epidermal growth factor receptor (EGFR)-mediated activations of MAPK, PI3K, and STAT3 signaling pathways demonstrate important mechanisms by which various ligands (i.e., EGF, TGF-α, amphiregulin, etc.)influence tumor growth, survival, and metastasis." (PMID 38539448, 2024). "Besides the genetic profile, expression patterns of GBM (e.g. EGFR expression) and, in particular, cells of the tumor microenvironment may substantially change over time and have a vast influence on the composition of the tumor tissue and amenability to therapy, further introducing complexity." (PMID 38899374, 2024). "A literature review revealed that several factors, including age, tumor size, tumor-node-metastasis (TNM) stage, epidermal growth factor receptor (EGFR) status, surgical approach, radiation therapy, and chemotherapy, can influence the prognosis of SRCC patients." (PMID 39497709, 2024). "No additional survival benefit was noted in EGFR WT tumor-bearing mice treated with saracatinib and TMZ." (PMID 38892466, 2024). "We provide a novel discovery that LUAD patients with tumor stages harboring MALAT1 (rs3200401; CC and CT+TT) heterozygotes had a significantly associated with EGFR wild-type, but not in all LADC patients." (PMID 38517388, 2024). "EGFR is a cell surface tyrosine kinase receptor that can recruit and phosphorylate cytoplasmic signaling molecules in an activated condition, and thereby initiate downstream signaling cascades, including PI3K/AKT, to promote tumor cell proliferation." (PMID 38711062, 2024). "In contrast, and EGFRvIII CAR-T expressing an EGFR TCE cleared the tumor, while the human skin graft showed no signs of immune infiltration." (PMID 39606234, 2024). "EGFR and FGFR2 play an essential role in tumor angiogenesis and, therefore, may increase the probability of hemorrhage, which may, in turn, lead to a poorer prognosis." (PMID 38877400, 2024). "The proliferation of tumor cells is primarily driven by TKRs, including members of the ERBB family (such as ERBB1/EGFR, ERBB2/HER2) and insulin-like IGF-1R, which activate oncogenic signalling pathways, including the PI3K/Akt/mTOR and MAPK/ERK pathways when overexpressed." (PMID 39199143, 2024). "No recurrent mutations, such as mutations in EGFR, KRAS, or AKT genes, were present in our tumor samples." (PMID 39199663, 2024). "The collaborative signaling among EGFR, PDGFRα, PDGFRβ, and FGFR2 proteins could result in a synergistic effect on promoting tumor progression making them valuable targets for cancer therapy." (PMID 38338684, 2024). "Despite elevation of EGFR activity as measured by this antibody, this did not correlate with increased tumor progression, perhaps because of the localization of the activity within the cell as opposed to just the overall activity." (PMID 39303037, 2024). "The in vivo studies reinforced these findings, showing significant tumor ablation in mice treated with the anti-EGFR-MPB nanocomposite and laser, with no adverse effects or recurrence." (PMID 39525484, 2024). "The preliminary pathology report from tumor tissue testing indicated no actionable alterations (wild type for EGFR, ALK, and ROS1)." (PMID 38920723, 2024). "Taken together, our data demonstrate that during the early stage of EGFR-targeted therapy, tumor cells can rapidly develop tolerance to osimertinib without acquiring new resistant mutations or activating MET." (PMID 39041204, 2024). "Moreover, AnxA1, known to regulate the nuclear localization of EGFR, promotes T cell dysfunction by favoring the EGFR/STAT3 transcriptional activities in cancer cells, enhancing immune evasion and tumor progression." (PMID 38645221, 2024). "Though antibody therapies directed at single receptors have been largely ineffective, the consistent expression of EGFR and HER2 in PDAC could be exploited to improve efficacy while reducing on-target/off-tumor dose limiting complications." (PMID 38650005, 2024).
tumor (continued). "The role of the tumor microenvironment and survival of EGFR negative malignant cells remain areas of concern for this strategy." (PMID 39364321, 2024). "Remarkably, separate recent work found skin injury activates EGFR signaling in wild type but not Ras-mutant cells, and the resulting differential proliferative boost acts as a tumor suppressing mechanism." (PMID 39636982, 2024). "Several studies have demonstrated that anti-EGFR antibodies such as Cetuximab and Panitumumab, coupled with near infrared (NIR) fluorescent dyes IRDye 800CW, allowed a better identification of tumor margins during FGS and improved an ex-vivo analysis of specimens." (PMID 38951897, 2024). "In non-TNBC cells, PDZK1 exerts a tumour-promoting effect by mediating the formation of the oestrogen receptor α (ERα)/EGFR/Src complex." (PMID 38604999, 2024). "The M27-derived CAR-T cells were found to effectively target and lyse EGFR-EGFRvIII-overexpressing tumour cells without observable toxicity on normal cells." (PMID 38660136, 2024). "In tumor tissue, the levels of 125I-LR004 remained relatively constant, with a peak concentration occurring as early as 4 h and sustained concentrations up to 10 days, indicating the targeted distribution tendency in EGFR-positive tumors." (PMID 38276624, 2024). "To test whether this association holds in recurrent tumors, we calculated the odds ratio (OR) for co-amplification of EGFR and CDK4 for each tumor." (PMID 38805346, 2024). "The CheckMate 9LA study was a phase III trial evaluating a novel regimen in 1150 treatment-naïve NSCLC patients without known sensitizing EGFR/ALK genomic tumor aberration." (PMID 39410008, 2024). "Thus, the strategy of simultaneously targeting EGFR and VEGFR-2 appears to be promising in the fight against cancer, acting synergistically to curb tumor growth and limit the formation of new blood vessels." (PMID 39598438, 2024). "Cetuximab prevents EGFR homo-dimerization/signaling, in contrast to trastuzumab which prevents hetero-dimerization of HER2 with other growth factors, leading to apoptosis of tumor cells in ovarian and breast malignancies." (PMID 38785789, 2024). "None of the tumours with EGFR expression above 6 fragments per kilobase of tanscript per million mapped reads were DDIR-positive." (PMID 38744099, 2024). "We report here for the first time the establishment and characterization of tumor xenograft mouse models with predefined HER2 and/or EGFR expression, and demonstrate that [64Cu]Cu-NOTA-trastuzumab Fab-PEG24-EGF bsRICs were able to exploit receptor heterogeneity for tumor imaging by PET." (PMID 38711454, 2024). "Tumors with constitutively activating mutations downstream of EGFR no longer rely on ligand-stimulated EGFR activation to potentiate downstream signaling, thus rendering EGFR-targeted mAbs ineffective in inhibiting cell proliferation and tumor growth." (PMID 40727266, 2024). "By confocal IF and ISH, EGFR overexpression was localized in our cases to not only epithelial cells, as we expected, but also to endothelial cells and infiltrating CD163+ macrophages in the dermis and the lamina propria in tumor-like ORF lesions." (PMID 38613413, 2024). "Notably, H4C1, EGFR, and ITGB1 maintained their prominence in terms of presentation levels across subpopulations stratified by HPV status and tumor stage." (PMID 39136024, 2024). "The advent of EGFR-TKIs has led to the emergence of precision medicine based on tumor molecular alteration profile as opposed to tumor histology or anatomy." (PMID 38233752, 2024). "Chen’s group also demonstrated that EGFR-CAR NK-92 cells(second-generation CAR) increased cytolysis and IFNγ production in breast cancer cell lines MDA-MB-231, MDA-MB-468, and MCF-7 (in vitro), and reduced tumor growth in tumor-bearing mice (in vivo)." (PMID 38245520, 2024). "Additionally, dinaciclib affects different cell growth regulators like EGFR and STAT3 on gene and protein level, thus decreasing tumor growth." (PMID 39668430, 2024).